ABCC2 (ATP binding cassette subfamily C member 2)
Diseases named in the same sentence as ABCC2 in open-access papers (continued):
Sharing a sentence is not in itself a finding about the gene and the disease.
lung cancer (15 papers, 1998 to 2024). A malignant neoplasm involving the lung. "The results showed that higher expression levels of ABCC2 were significantly associated with poor overall survival (OS) (P < .01) in lung cancer (1925 samples)." (PMID 32815556, 2021). "Similarly, the increased expression of ABCC2 was significantly associated with progression‐free survival (PFS) (P < .001) in lung cancer (982 samples)." (PMID 32815556, 2021). "Overexpression of ABCC2 and Bcl-xL has been observed in cisplatin-resistant lung cancer (A549/DDP) cells." (PMID 36778005, 2023). "Our study suggests that ABCC2 has potential as a therapeutic target for the treatment of patients with DDP‐resistant lung cancer." (PMID 32815556, 2021). "Although there are inconsistencies in the literature, previous reports also support a link between genetic variations in the ABCC1 and ABCC2 genes, altered irinotecan pharmacokinetics and clinical outcomes in colon and lung cancer patients." (PMID 29066969, 2017). "Further, recent study associated SNP rs9524885 in MRP4/ABCC4 (as well as rs2756109 in MRP2/ABCC2) with pain in nonsmall-cell lung cancer patients." (PMID 23766564, 2013). "Hence, altering the expression of Let-7c can bring back the sensitivity of cisplatin in lung cancer cells by targeting ABCC2 and Bcl-xL." (PMID 36778005, 2023). "ABCC2 is expressed at low levels in normal lung tissue and at high levels in lung cancer." (PMID 27988838, 2017). "The knockdown ABCC2 could reverse cisplatin resistance in lung cancer cells." (PMID 37589509, 2023). "Multiple studies have demonstrated that ABCC2 and PFKP play a carcinogenic role in the development of lung cancer." (PMID 39148731, 2024). "Our previous observations on lung cancer cells NCI-H460 overexpressing ABC transporter proteins (LRP, ABCB1, BCRP, ABCC1 ABCC2 and ABCC3) confirmed the ability of resveratrol lignans to overcome the resistance to PTX." (PMID 27304668, 2016). "We next analyzed mRNA expression of ABCC2 in lung cancers and noncancerous lung tissues (control subjects) using The Cancer Genome Atlas (TCGA) RNA-Seq dataset, and found that its expression was significant up-regulated in LUADs and LUSCs compared with control subjects." (PMID 39309428, 2024).
colorectal cancer (12 papers, 2015 to 2026). A primary or metastatic malignant neoplasm that affects the colon or rectum. "Our results showed that combined analysis of UGT1A1*28 and *6 polymorphisms and ABCC2 c.3972C > T were closely related with neutropenia toxicity in Thai colorectal cancer patients." (PMID 32778670, 2020). "ABCB1, ABCC1, and ABCC2 mRNA levels were compared between Caco-2 cells and other colorectal cancer cell lines (HCT-15, LoVo, DLD-1, HCT-116, SW620)." (PMID 41557172, 2026). "For example, ABCC2 mRNA levels are positively correlated with cisplatin resistance in colorectal carcinoma." (PMID 27487151, 2016). "Metastatic colorectal cancer patients without the ABCC2 c.-24T variant showed an increased overall response rate and median progression-free survival (p = 0.031)." (PMID 41385496, 2025). "ABCC2, ATP Binding Cassette Subfamily C Member 2, acts as a key transporter in support of cell energy transition and proliferation and was identified as a pro-oncogenic factor in colorectal cancer." (PMID 36829161, 2023). "Therefore, the aim of this study was to extensively investigate the association between genetic polymorphisms in CYP3A4/5, DPYD, UGT1A1, ABCB1, ABCC2, and ABCG2 and irinotecan induced-toxicity in cohort of Thai colorectal cancer patient." (PMID 32778670, 2020). "Thus, the aim of this study was to assess the allele and genotype frequencies and the relationship between CYP3A4/5, DPYD, UGT1A1, ABCB1, and ABCC2 genetic variations and irinotecan-induced toxicity in Thai colorectal cancer patients." (PMID 32778670, 2020). "In the multidrug-resistant, human colorectal carcinoma (CRC) cell line HCT-116/L-OHP overexpressing efflux transporter ABCC2, miR-297 level was found to be reduced." (PMID 39114355, 2024).
melanoma (11 papers, 2015 to 2025). A malignant, usually aggressive tumor composed of atypical, neoplastic melanocytes. "We showed here that high ABCC2 expression was associated with unfavourable OS in melanoma (SKCM)." (PMID 33202946, 2020). "High levels of ABCC2 expression in melanoma cells and other cancer cells can lead to increased resistance to chemotherapy drugs, thus reducing treatment efficacy and leading to poorer prognosis." (PMID 39213172, 2024). "By machine learning algorithms, we identified 6 key CRGs (ABCC2, CA14, EGR3, FBXW7, LDHB, and PSEN2) closely associated with melanoma." (PMID 39213172, 2024). "In a prior study, cisplatin-resistant melanoma cells displayed a distinguishable elevated expression of (MRP2/ABCC2), which was reflected by a decrease in cisplatin cytotoxicity in terms of a decline in the drug’s ability to form intra-strand DNA cross-links." (PMID 36650399, 2023). "The last examined transporter, ABCC2, is responsible for drugs’ efflux and is described in the literature in the context of the emergence of drug resistance and in the occurrence in melanoma." (PMID 39175042, 2024). "Finally, by comparing the feature genes identified by the three machine learning approaches, six common key CRGs were identified as melanoma-related key CRGs, including ABCC2, CA14, EGR3, FBXW7, LDHB, and PSEN2." (PMID 39213172, 2024). "Compared to normal skin tissues, 4 key CRGs (ABCC2, CA14, LDHB, PSEN2) were significantly upregulated while 2 key CRGs (EGR3, FBXW7) were significantly downregulated in melanoma tissues." (PMID 39213172, 2024). "Among them, 4 key CRGs (ABCC2, CA14, LDHB, PSEN2) were significantly upregulated and 2 key CRGs (EGR3, FBXW7) were significantly downregulated in melanoma tissues." (PMID 39213172, 2024). "Further, we and others have shown a direct effect of GH–GHR action in upregulating expression of ATP-cassette-containing (ABC) multidrug efflux pumps such as ABCB1, ABCC1, ABCC2, and ABCG2 in melanoma as well as in breast cancer." (PMID 31547367, 2019). "It was previously shown that GH action in GHR+ human melanoma cells upregulates while GHR knockdown suppresses the ABC-transporter system, especially ABCB1, ABCB5, ABCB8, ABCC1, ABCC2, ABCG1, and ABCG2 differentially in a drug-dependent manner." (PMID 31547367, 2019). "In human melanoma cells, coexistence of ABCB1, ABCG2, and ABCC2 together with stem cell markers on the cell surface was observed in a subset of cells." (PMID 28623509, 2017). "A tenuous correlation was shown in melanoma cells revealing co-expression of ABC transporters, ABCB5 and ABCC2 and hTERT." (PMID 28623509, 2017). "ABCB5 expression in tumor cells was seen to correlate with clinical melanoma progression and a subpopulation of human melanoma cells was observed to coexpress ABCB1, ABCB5, and ABCC2 in addition to stem cell markers." (PMID 26649310, 2015). "Additionally, we showed that the protein levels of ABCC1, ABCC2, ABCB1, and ABCG2 were elevated in presence of GH treatment in parent melanoma cells (Malme-3M and SK-MEL-28)." (PMID 39123364, 2024). "Specifically, high expression of 4 key CRGs (ABCC2, CA14, LDHB, PSEN2) was significantly correlated with poor prognosis in melanoma patients (HR>1, P<0.05), while low expression of 2 key CRGs (EGR3, FBXW7) was significantly associated with poor prognosis (HR<1, P<0.05)." (PMID 39213172, 2024).
neutropenia (10 papers, 2014 to 2025). A decrease in the number of neutrophils found in the blood. "After Bonferroni correction, our study observed that only the ABCC2 c.-24C > T (rs717620) variant was significantly associated with all-grade neutropenia in the second cycle." (PMID 41385496, 2025). "Specifically, the ABCC2 variant (rs3740066) is significantly associated with grades 1–4 neutropenia during the first treatment cycle in the Thai population treated with irinotecan." (PMID 41385496, 2025). "The ABCC2 c.-24C > T polymorphism was significantly associated with all-grade neutropenia in the second cycle (p = 0.001)." (PMID 41385496, 2025). "The ABCC2 c.3972C > T was significantly associated with grade 1–4 neutropenia (P < 0.012) at the first cycle." (PMID 32778670, 2020). "In conclusion, combination of UGT1A1*28 and *6 and ABCC2 c.3972C > T genotype are associated with the occurrence of grade 1–4 and severe neutropenia in Thai patients with metastatic colorectal cancer who receive irinotecan-based chemotherapy." (PMID 32778670, 2020). "At the first cycle of treatment, ABCC2 c.3972C > T was significantly associated with all grades neutropenia [grade 1–4 neutropenia; odds ratio (OR) 3, 95% confidence intervals (CI) 1.3–7; P < 0.012]." (PMID 32778670, 2020). "The result showed that ABCC2 c.3972C > T was significantly associated with grade 1–4 neutropenia (P = 0.015)." (PMID 32778670, 2020). "Multivariate analysis indicated that ABCC2 c.3972C > T is a risk factor for the occurrence of grade 1–4 neutropenia at the first cycle in patients who receive irinotecan-based chemotherapy." (PMID 32778670, 2020). "The second ABCC2 polymorphism in our study that influenced severe neutropenia and early nausea risk was the silent change p.Ile1324= (rs3740066)." (PMID 29507678, 2018). "A Japanese study demonstrated that carriers of the variant allele for rs12762549 (ABCC2,101620771 C > G) had an increased risk to develop docetaxel-induced leukopenia/neutropenia in 84 patients." (PMID 25881102, 2015). "UGT1A1*6 and ABCC2 -24C > T variants emerge as potential predictors of irinotecan-induced neutropenia, while UGT1A1*6 and SLCO1B1 521T > C may serve as markers of prolonged PFS in Thai patients." (PMID 41385496, 2025). "In conclusion, UGT1A1*6 and ABCC2 -24C > T polymorphisms may serve as predictors of irinotecan-induced neutropenia, while UGT1A1*6 and SLCO1B1 521T > C are associated with improved progression-free survival in Thai patients." (PMID 41385496, 2025). "Interestingly, our result suggested that ABCC2 c.3972C > T is associated with grade 1–4 neutropenia at the first cycle." (PMID 32778670, 2020). "Applying the stringent Bonferroni correction (p value < 0.002), our findings demonstrated a significant association between irinotecan-induced neutropenia and the UGT1A1*6 and UGT1A1 phenotypes, as well as the ABCC2 c.-24C > T variant, in relation to toxicity." (PMID 41385496, 2025). "Since variants of not only UGT1A1, but also other genes, including UGT1A7, UGT1A9, ABCB1 and ABCC2, have been reported to be involved in the occurrence of CPT-11-induced severe neutropenia, rare variants of these genes should be investigated in the future." (PMID 24932285, 2014). "The target study also found that only heterozygous ABCC2 c.-24C>T, but not homozygous carriers reduced the risk of neutropenia." (PMID 28397089, 2017).
Hyperbilirubinemia (9 papers, 2013 to 2025). An increased amount of bilirubin in the blood. "For example, the ABCC2 rs717620 T variant is associated with an increased risk of hyperbilirubinemia and mortality in patients with drug-induced liver injury." (PMID 36278153, 2022). "The two DJS patients with ABCC2 p.G693R mutation, which was conserved among different species, showed typical hyperbilirubinemia phenotype." (PMID 32183854, 2020). "Whole exome sequencing for mutations in other known hyperbilirubinemia-related genes was conducted for the cases with ABCC2 p.G693R." (PMID 32183854, 2020). "Mrp2−/−mice are viable but, like ABCC2-knockout rats, showed chronic hyperbilirubinemia followed by a reduction in biliary excretion of bilirubin glucuronides." (PMID 37255458, 2023). "In conclusion, here we show that the ABCC2 p.G693R mutation causes dysfunction of the MRP2 protein and may result in hyperbilirubinemia in DJS in China." (PMID 32183854, 2020). "In the present study, whole exome sequencing revealed additional HSD3B7 p.R110Q mutation in a case with ABCC2 p.G693R mutation, but no mutations in the other known hyperbilirubinemia-related genes in the other case with ABCC2 p.G693R mutation." (PMID 32183854, 2020). "In patient No. 1 with ABCC2 p.G693R mutation, whole exome sequencing revealed no mutations in the other known hyperbilirubinemia-related genes." (PMID 32183854, 2020).
colon cancer (8 papers, 2016 to 2025). "ABCC2 rs717620 (C-24T) CC genotype present increased rate of grade 3-4 thrombocytopenia in contrast to CT and TT genotypes in 292 colon cancer patients treated with FOLFOX chemotherapy (5.6% vs. 0.8%, p = 0.047)." (PMID 39234108, 2024). "Data from the flow cytometric transporter efflux assay showed specific inhibition of ABCC2 activity by vatalanib in stable transfected cells and ABCC2-overexpressing oxaliplatin-resistant colon cancer cells HCT116/Oxa." (PMID 27014726, 2016). "Complementary to this, human colon cancer cell lines may also express other efflux transporters, such as ABCG2 (breast cancer resistance protein, BCRP), ABCC3 (multidrug resistance-associated protein 3, MRP3) and ABCC2 (multidrug resistance-associated protein, MRP2)." (PMID 36983038, 2023).
intrahepatic cholestasis (7 papers, 2014 to 2024). A cholestasis characterized by impairment of the bile flow caused by obstruction located in the liver. "The reduced expression of the canalicular transporters ABCC2, ABCG2 and of the cholesterol transporter ABCG5 leads to impaired bile acid, bilirubin and cholesterol excretion and in the long term to intrahepatic cholestasis as was observed in DILI patients treated with diclofenac." (PMID 29296203, 2017).
non-small cell lung carcinoma (7 papers, 2013 to 2025). A group of at least three distinct histological types of lung cancer, including non-small cell squamous cell carcinoma, adenocarcinoma, and large cell carcinoma. "ABCC2 expression is upregulated in non small cell lung cancer cells (H322) overexpressing CD44, which are more resistant to cisplatin when cultured on a HA matrix." (PMID 24124770, 2013). "Concerning clinical efficacy, previous studies have shown that patients with the ABCC2 c.-24T homozygous genotype had significantly better response rates and progression-free survival in non-small-cell lung cancer patients treated with irinotecan and cisplatin." (PMID 41385496, 2025). "Furthermore, CD44 increased chemoresistance in non-small cell lung cancer by upregulation of ABCC2." (PMID 29371972, 2017). "In non-small-cell lung cancer (NSCLC), elevated ABCC2 expression in cisplatin-resistant A549 cells promotes drug resistance by facilitating drug efflux and inhibiting apoptosis." (PMID 40429829, 2025). "HA (molecular weight not specified) also promoted expression of ABCC2 in non-small cell lung cancer cells." (PMID 31443261, 2019).
osteosarcoma (6 papers, 2017 to 2025). A usually aggressive malignant bone-forming mesenchymal neoplasm, predominantly affecting adolescents and young adults. "In survivors of ALL or osteosarcoma, carrying the ABCC2-rs3740066-GG genotype or the SLC22A6-rs6591722-AA genotype increased the risk of cardiomyopathy 5–10 years after cancer diagnosis compared to other genotypes (p = 7.11 × 10−4, p = 1.71 × 10−3, respectively)." (PMID 40413218, 2025). "Four members of ABC family have been shown to contribute to multidrug resistance in osteosarcoma, including MDR1 (also called P-glycoprotein, P-gp or ABCB1), multidrug resistance-associated protein 1 and 2 (MRP1/ABCC1 and MRP2/ABCC2), and breast cancer resistance protein (BCRP/ABCG2)." (PMID 35955749, 2022). "ABCC2 is a frequently investigated gene for instance in drug-related toxicities, in therapy-response, resistance against various drugs, in carcinogenesis and in the outcomes of osteosarcoma and leukemia." (PMID 29970035, 2018).
pancreatic cancer (6 papers, 2017 to 2024). "In pancreatic cancer patients, overexpression of ABCC2 along with SLC22A3 in a combination was detected." (PMID 33865438, 2021). "Protein localization and brush border staining intensity of ABCC2 and SLC22A3 was assessed in tumor tissue blocks of 65 pancreatic cancer patients and associated with clinical data and survival of patients with regard to therapy." (PMID 31874997, 2019). "Three out of them (ABCC2, ABCC5, ABCC8) have been already described for their association with drug resistance in pancreatic cancer." (PMID 29285254, 2017). "Overexpression of ABCC2 was previously reported in pancreatic cancer." (PMID 33865438, 2021). "One recent large-scale, multicentre clinical trial showed ABCC2 genetic polymorphisms are associated with worse overall survival in stage I pancreatic cancer, but there is no detailed information regarding the therapies which the patients had received." (PMID 31500349, 2019). "Overexpression of circFARP1 in CAFs confers GEM resistance in pancreatic cancer cells by enhancing the expression and secretion of LIF in CAFs, thereafter activating the STAT3 signaling pathway and increasing the expression of several GEM resistance-associated factors, including ABCC2, CDA and SOX2." (PMID 35045883, 2022). "We further determined that the circFARP1/LIF axis remarkably increased the expression of GEM resistance-related genes, such as ABCC2, CDA, and SOX2, and induced GEM resistance in pancreatic cancer cells." (PMID 35045883, 2022). "This study investigated significance of protein expression and cellular localization of the previously suggested putative prognostic markers ABCC2 and SLC22A3 in pancreatic cancer patients." (PMID 31874997, 2019). "Gene expression profile analysis and further experiments showed that circFARP1 conferred GEM resistance by enhancing LIF expression and secretion in CAFs, thereafter increasing the expression of ABCC2, CDA and SOX2 by activating the STAT3 signaling pathway in pancreatic cancer cells." (PMID 35045883, 2022).
acute lymphoblastic leukemia (4 papers, 2014 to 2023). Leukemia with an acute onset, characterized by the presence of lymphoblasts in the bone marrow and the peripheral blood. "In particular, the overexpression of MRP1 (ABCC1), MRP2 (ABCC2), MRP3 (ABCC3), MRP5 (ABCC5), and MRP6 (ABCC6) correlates with a poor prognosis in acute lymphoblastic leukemia in both adults and children." (PMID 36978873, 2023). "It has been reported that ABCC1, ABCC2, ABCC3, ABCC4, ABCC5 and ABCC6 play a significant role in MDR mediated non-small cell lung cancer (NSCLC), breast cancer, prostate cancer, colorectal cancer, ovarian cancer and acute lymphoblastic leukemia (ALL)." (PMID 25191874, 2014).
anemia (4 papers, 2014 to 2024). A reduction in the number of red blood cells, the amount of hemoglobin, and/or the volume of packed red blood cells. "In particular, rs1128503 (ABCB1, C > T), rs12762549 (ABCC2, C > G), rs363717 (ABCA1, A > G) and rs11615 (ERCC1, T > C) were significantly associated with grade 3–4 anemia (p = 0.035, OR 1.58; p = 0.005, OR 0.55; p = 0.001, OR 1.31 and p = 0.024, OR = 1.58)." (PMID 25881102, 2015). "The −24T allele in ABCC2 gene was significantly associated with higher risks of high-grade hematologic (leucopenia, anemia, and thrombocytopenia) and non-hematologic (gastrointestinal and mucosal damage/oral mucositis) MTX toxicities." (PMID 24404132, 2014). "Indeed, we found that the −24T allele in ABCC2 was significantly associated with higher risks of high-grade hematologic (leucopenia, anemia, and thrombocytopenia) and non-hematologic (gastrointestinal and mucosal damage/oral mucositis) MTX toxicities in childhood ALL patients." (PMID 24404132, 2014).